RNU6-563P (RNA, U6 small nuclear 563, pseudogene)
Gene: Small nuclear RNA gene on chromosome 20 (47,492,978 to 47,493,085, reverse strand). Ensembl gene ENSG00000201742.
Homologues: Orthologues: chimpanzee U6 (98% identical), macaque U6 (93% identical), dog U6 (81% identical), rabbit U6 (77% identical), zebrafish U6 (71% identical). Paralogues in human: RNU6-1010P (85% identical), RNU6-477P (85% identical), RNU6-1035P (83% identical), RNU6-181P (83% identical), RNU6-618P (83% identical), RNU6-73P (83% identical), RNU6-812P (83% identical), RNU6-1235P (82% identical), RNU6-144P (82% identical), RNU6-15P (82% identical), RNU6-188P (82% identical), RNU6-20P (82% identical), and 1286 more.